RN7SKP292 (RN7SK pseudogene 292)
Gene: Miscellaneous RNA gene on chromosome 4 (6,997,012 to 6,997,328, forward strand). Ensembl gene ENSG00000202392.
Homologues: Orthologues: chimpanzee 7SK (99% identical). Paralogues in human: 7SK (86% identical), RN7SKP174 (84% identical), RN7SKP118 (84% identical), RN7SKP187 (83% identical), RN7SKP48 (83% identical), RN7SKP185 (79% identical), RN7SKP178 (78% identical), RN7SKP55 (78% identical), RN7SKP62 (78% identical), RN7SKP227 (77% identical), RN7SKP76 (77% identical), RN7SKP104 (74% identical), and 284 more.